EGFR (epidermal growth factor receptor)
Diseases named in the same sentence as EGFR in open-access papers (continued):
Sharing a sentence is not in itself a finding about the gene and the disease.
tumor (continued). "The opposite results were obtained when EGFR kinase activity was inhibited with gefitinib, supporting EGFR modulation as an important “switch” in determining tumor outcomes in a manner dependent on both time of intervention and the underlying disease state." (PMID 29904166, 2018). "In a recent study on cell-free circulating tumor DNA (cftDNA), Del Re and colleagues evaluated the appearance of KRAS mutations in EGFR positive NSCLC patients progressed after a TKI regimen." (PMID 29464099, 2018). "The Eps8 gene was originally identified as a substrate for the EGFR kinase, which is known to promote tumor progression through an EGFR-dependent pathway." (PMID 29515106, 2018). "Tumours that have the wild type EGFR are resistant to EGFR-directed TKIs, such as erlotinib and gefitinib." (PMID 30544701, 2018). "Among the overlapping genes, we extracted CDK2, CDK6, and EGFR, which are all known to promote tumor cell growth." (PMID 29540837, 2018). "Studies have been delineating that, 80% of the tumor that expresses EGFR basal marker in a western population." (PMID 30408068, 2018). "Stat3 is activated by mutant EGFR and JAK, and notably, pStat3 is associated with tumor cell proliferation and angiogenesis." (PMID 30174790, 2018). "In particular, EGF signaling via the EGFR can stimulate tumor cell proliferation and promote bone metastasis in PC." (PMID 29890952, 2018). "Adjacent tumor sections of both AsPC-1 and BxPC-3 were evaluated for EGFR and HER3 expression by immunohistochemistry." (PMID 29899472, 2018). "As predicted, cells from EGFR-amplified tumors appear more heterogeneous in their baseline migratory behavior, with an expansion in the sub-population of migrating tumor cells that travel the farthest and fastest." (PMID 30573757, 2018). "Our data suggest that the TF-FVIIa-PAR2 signaling axis cooperates with EGFR, revealing the presence of a positive feedback loop that favors tumor progression." (PMID 30093972, 2018). "Inhibition of FASN with Orlistat induces EGFR ubiquitination and abrogates EGFR mutant signaling, and reduces tumor growths both in culture systems and in vivo." (PMID 29449326, 2018). "In the present study, we aimed to understand the role of EGFR during OS development using the autochthonous H2‐c‐fosLTR mouse model and human OS tumor biopsies." (PMID 30361264, 2018). "Tumor cells are resistant to all EGFR TKIs when the EGFR p.Cys797Ser and p.Thr790Met resistance mutations are located on the same allele, i.e., in cis-position." (PMID 29890761, 2018). "On the other hand, concurrent delivery of EGFR-1 and EGFR-2 siRNAs with carbonate apatite exerted significant tumor volume reduction (61%) in contrast to control groups." (PMID 29861465, 2018). "By using an established xenograft mouse tumor model, the functionality of the monovalent α-EGFR TM and the bivalent α-EGFR-EGFR TM was finally compared in vivo." (PMID 29876011, 2018). "In patient’s biopsies, molecular weights of EGFR varied from patient to patient (tumor specimens 830, 831, 836, 837, 840, and 844 above 170 kDa; tumor specimens 839, 842, and 843 about 170 kDa)." (PMID 29855336, 2018). "A bivariate two-sided Spearman’s rank correlation showed a significant correlation between HIF-1α mRNA and EGFR mRNA expression in tumor tissues (correlation coefficient: +0.69; p < 0.001)." (PMID 30513863, 2018). "It was possible to target exosomes expressing an epidermal growth factor receptor (EGFR)-binding peptide to tumor cells." (PMID 29704899, 2018). "In this study, we investigated the anti-tumor activity of afatinib, an irreversible pan-EGFR inhibitor, combined to cisplatin in different schedules of exposure." (PMID 30345256, 2018). "When EGFR is activated, Socs36E functions as a tumor suppressor in epithelia and, similarly, depletion of SOCS5 function has a synergistic effect on cell transformation when combined with activation of EGFR or Ras/MAP kinase signaling in human cell culture." (PMID 30558204, 2018).
tumor (continued). "In this study, we developed a NIR fluorescent dye-labeled nimotuzumab immunoconjugate, IRDye800CW-nimotuzumab, and evaluated in vitro binding with EGFR-positive cells, in vivo tumor uptake by NIR fluorescent imaging, and ex vivo biodistribution." (PMID 29464066, 2018). "A focal amplification of EGFR was observed in the primary tumor, pre- and post-treatment PDXs, the recurrent tumor, and, despite low purity, the metastasis sample." (PMID 30134176, 2018). "Such activating FcγRs present on neutrophils include FcγRI, only present after neutrophil activation, and FcγRIIa, which appears to be the main receptor required for ADCC against cancer cells expressing the tumor antigens HER2/Neu or EGFR." (PMID 30761158, 2018). "EGFR signaling plays a crucial role in tumor biology by modulating cellular proliferation, angiogenesis, metastasis, and survival of cancer cells." (PMID 29926131, 2018). "Exosomes expressing the amphiregulin (AREG), isolated from several tumor cells, have been found able to activate the Epidermal Growth Factor Receptor (EGFR) in receiving cells thus affecting the bone marrow microenvironment or promoting bone metastases." (PMID 30591649, 2018). "PGE2 can induce tumor progression through epidermal growth factor receptor (EGFR) signaling and increased proliferative responses in lung ADC." (PMID 29170806, 2018). "Chen and colleagues highlighted this with examples such as epidermal growth factor receptor (EGFR) which is over-expressed in some tumors and has an important role in tumor progression." (PMID 30469350, 2018). "KRAS mutations undermine EGFR-targeted therapies and variant KRAS-mutant tumor cells contribute to the outgrowth of EGFR-resistant tumor cell populations." (PMID 30283732, 2018). "It is also possible to push CSC differentiation by blocking BMP and EGFR mediated signals, to prevent tumor vascularization by inhibiting VEGF, to increase tumor sensitivity by interfering with niche adhesion molecules (N-Cadherin and VCAM1)." (PMID 30510501, 2018). "EGFR can affect the tumor cell differentiation, proliferation, survival, adhesion, apoptosis, and migration." (PMID 29765324, 2018). "Using an in vivo Drosophila tumor model, we identified an aldehyde dehydrogenase as a potential tumor suppressor that cooperated with EGFR." (PMID 30486822, 2018). "EGFR activation also plays a role in resistance to chemotherapy and radiation treatment in tumor cells." (PMID 29377763, 2018). "Major receptors or pathways involved in immunomodulation include vascular endothelial growth factor receptor (VEGFR), epidermal growth factor receptor (EGFR), as well as PD-L1 on tumor cells and the receptors PD1 and CTLA-4 on the site of T cells." (PMID 30577587, 2018). "Anti–EGFR-GNs are an active PAI contrast agent that selectively binds to EGFR-positive tumor cells in primary tumor mass and regional metastatic LN." (PMID 29484119, 2018). "A total of 16 nonsynonymous mutations in genes other than EGFR and HER2 was detected in the 22 patients, for a mean of 0.7 such mutations per tumor." (PMID 29765525, 2018). "Collectively, our work identifies decreased OGN expression in CRC impaired EGFR internalization as a novel mechanism through which tumor cells induce EGFR activity to sustain proliferative signaling." (PMID 29499765, 2018). "We have also focused on the development of bispecific antibodies for cancer treatment and have reported the marked in vitro and in vivo anti-tumor activity of hEx3-Db, a humanized bispecific Db targeting epidermal growth factor receptor (EGFR) and CD323." (PMID 30467410, 2018). "A fluorescently-labeled anti-EGFR antibody (cetuximab) is clinically well tolerated and efficiently differentiates tumor from normal tissue." (PMID 29992954, 2018). "To elucidate the ligand responsible for activation of EGFR, we examined the effects of the tumour‐promoting DCA on AREG, TGF‐α and HB‐EGF by ELISA assay in IMCE and HCT‐116 cell lines." (PMID 29956475, 2018).
tumor (continued). "When tumor progression was detected under afatinib, six patients (all except patient 6) met Jackman’s criteria for acquired resistance to first line EGFR-TKI treatment." (PMID 30550608, 2018). "Moreover, tumor spatial heterogeneity may also lead to discrepancies in EGFR mutation status." (PMID 29643378, 2018). "Under the chosen experimental conditions, UniCAR-modified T cells armed with the monovalent α-EGFR TM were able to completely eliminate the injected tumor cells." (PMID 29876011, 2018). "By realization of two bioactivity-enhancing principles in one molecule, i.e. hexa- or dodecavalent configuration of TRAIL and binding to EGFR-positive tumour cells, IgG-scTRAIL combines efficient cell death induction in tumour cells with targeted delivery." (PMID 29773864, 2018). "TBR of can225-IR700 was high in tumor due to specific APC binding to EGFR expressing TCC SH cells, while TBR was high in liver likely due to non-specific accumulation of can225-IR700 conjugate as the liver is not known to express EGFR." (PMID 29721181, 2018). "In particular, hyperactivation of EGFR-dependent signal transduction usually accompanies tumor development and leads to unfavorable clinical prognosis." (PMID 30518879, 2018). "This immune response depends on the immunogenic cell death induced by the mAb mediated inhibition of EGFR signaling, which likely stimulate tumor-antigen presentation by dendritic cells in vivo." (PMID 29844873, 2018). "Ex vivo analysis showed that both nonlabeled NCm100 and cetuximab-labeled NCm100 have accumulated in the vascular area of the tumor regardless the availability of EGFR." (PMID 30515065, 2018). "Epidermal growth factor receptor (EGFR), a tumor oncogene is involved in the regulation of many cellular responses, including cell proliferation, apoptosis, and cellular differentiation." (PMID 29719621, 2018). "Activation of EGFR is also mediated by type 1 insulin-like growth factor (IGF) and extracellular matrixes, which are produced by the tumor-associated microenvironment during PCa metastases in the bone marrow." (PMID 30134822, 2018). "Molecular alterations including KRAS mutations, EGFR mutations, and ALK/ROS1 re-arrangements were detected in 23.2%, 19.6%, and 5.4% of analyzed tumor samples, respectively." (PMID 29707129, 2018). "In preclinical studies, a single dose of RN765C at 1.5-3 mg/kg was generally sufficient to induce tumor regression in multiple cell line and patient-derived xenograft models, including those that are resistant to EGFR-directed tyrosine kinase inhibitors." (PMID 30323890, 2018). "And, these mutations and continuously activated Rab35Q67L mutation can inhibit apoptosis, suggesting that Rab35 is involved in EGFR-mediated tumor progression." (PMID 30524285, 2018). "Tumor-bearing lung tissues from mice expressing EGFR or Kras oncogenes produce higher levels of Dusp6 RNA than do normal lung controls or tumor-bearing lungs from mice with a MYC transgene." (PMID 30475204, 2018). "A tissue biopsy was collected when a patient with an initial RAS/BRAF WT tumour developed secondary resistance to anti-EGFR-based therapy." (PMID 29895949, 2018). "In contrast, EGFR-TKIs can be administered safely even to patients with a poor ECOG PS, and they are associated with a higher tumor response rate and shorter time to response compared with chemotherapy." (PMID 30034636, 2018). "In clear cell RCC, the miR-514a-3p expression level was significantly downregulated and behaves as a tumor suppressor through its targeting of epidermal growth factor receptor (EGFR)." (PMID 29928475, 2018). "According to PET experiments in vivo, the increased avidity of the bivalent α-EGFR-EGFR TM improves the enrichment at the tumor site and its use for PET imaging." (PMID 29876011, 2018). "Immunohistochemistry of tumor sections revealed that the phosphorylated form of EGFR was significantly decreased within 6 h after a single administration of M-COPA." (PMID 29416720, 2018).
tumor (continued). "Currently, several advancing clinical trials are conducted to assess the availability of combining the MET-targeted drugs (MET-TKIs or MET-MAbs) with EGFR TKIs in the treatment of EGFR-mutant tumor with MET-amplification." (PMID 29455669, 2018). "In EGFR-mutated NSCLC, pre-clinical models have suggested a role of the Shh pathway activation in tumor progression with EGFR tyrosine kinase inhibitors (TKIs)." (PMID 29581874, 2018). "Overall, our data implied that suppression of EGFR signaling pathway is involved in oxymatrine‐induced tumor inhibition in NSCLC." (PMID 29239135, 2018). "This clinical effect seems to be particularly evident in RAS wild type tumours, and for patients treated with anti-EGFR agents, while the survival differences by primary tumour side are less clear for anti-VEGF agent-treated patients." (PMID 29416820, 2018). "Particularly, the combination of gemcitabine followed by gefitinib (an inhibitor of the epidermal growth factor receptor) has been found to be more effective in tumor growth control than the reverse drug application." (PMID 30647839, 2018). "We harvested cells from residual tumor nodules from mice treated with ErbB3 antibody for five weeks and measured levels of activated EGFR in residual tumor cells (i.e., persister cells)." (PMID 29305574, 2018). "The mTORC1 pathway intersects with key mitogenic signals driving tumor development, such as mutations of PI3K, EGFR, K-ras, or loss of phosphatase and tensin homolog (PTEN), which can also lead to hyperactivation of mTORC1 in numerous human cancers." (PMID 30266942, 2018). "The depletion of prp8 efficiently blocked Ras-, EGFR- and Notch-driven tumours but, in contrast, enhanced tumours that were driven by oncogenic RET, suggesting a context-specific role in hyperplasia." (PMID 30333215, 2018). "Multiple studies characterize these PDX models and report maintenance of patient morphologic and molecular characteristics including EGFR amplification as well as tumor invasiveness." (PMID 30050899, 2018). "EGFR contributes to the differentiation, proliferation, survival, migration and invasiveness of cancer cells and increases tumor angiogenesis." (PMID 30016965, 2018). "Lately, a simple clinical feature, the primary tumour location (right vs left colon), has been demonstrated to have a significant impact on prognosis, and perhaps on the efficacy of anti-EGFR agents, in wild type colorectal cancer patients." (PMID 29416820, 2018). "In vivo, Onc.Ad-EGFR.BiTE combined with two administrations of FR.CAR-T cells significantly delayed tumor growth in a xenograft model in which the tumor cells expressed intermediate levels of FR-α and high levels of EGFR." (PMID 30298067, 2018). "In preclinical studies, afatinib demonstrated more prolonged suppression of receptor kinase activity compared to reversible first-generation EGFR-TKIs and it also showed activity in tumor cells resistant to reversible EGFR inhibitors." (PMID 30345256, 2018). "In an EGFR-driven pipsqueak knockdown neoplastic tumour model, EGFR signalling induces upregulation of Wg, which promotes epithelial tumour cell proliferation, but tumour growth is dependent on the neighbouring myoblast cells." (PMID 29693007, 2018). "Combined, these data indicate that gefitinib blocks an EGFR dependent bursting behavior present within a subset of migratory tumor cells." (PMID 30573757, 2018). "High expression of EGFR correlates with advanced stage of tumour development and poor response to chemotherapy." (PMID 30388834, 2018). "Due to the inverse relationship of hsa-miR-7 with CDR1-AS, CDR1-AS can be expected to be expressed at higher levels in EGFR-high tumours, and this was the case in our dataset." (PMID 29941867, 2018).
tumor (continued). "Two studies sought to detect emerging resistance to anti-EGFR therapy using sequential analysis of circulating tumor DNA for KRAS status." (PMID 30234115, 2018). "According to our in vitro data, Orlistat treatment induced significant tumor volume reduction versus vehicle‐exposed animals, in mice carrying EGFR mutant PC‐9GR and H1975 xenografts, by 58 and 49%, respectively." (PMID 29449326, 2018). "The results showed that reduced HCRP-1 expression promoted tumor metastasis and activated the EGFR and AKT signaling pathway, which were consistent with the results in vitro." (PMID 30518879, 2018). "EGFR belongs to a family of cell membrane receptor tyrosine kinases and is a key factor in tumour cell growth and invasion." (PMID 30138363, 2018). "The drug reduces EGFR autophosphorylation in intact tumor cells at a median inhibitory concentration of 20 nM although this ranges from 5 (nM) and 6 (nM) in exon 19 deletion and L858R cell models respectively to >2,000 (nM) in T790M models." (PMID 30018881, 2018). "This group also discovered that the overexpression of micro-RNAs, mir-10, or mir-375, cooperates with overexpression of EGFR in promoting invasive overgrown tumours." (PMID 29693007, 2018). "In fact, the combined administration of RAF and EGFR inhibitors initially induces tumor regression in most patients, but acquired resistance invariably develops, typically within six months." (PMID 29652830, 2018). "In conclusion, the combination of retargeting and shielding improved the tumor-to-liver ratio upon intratumoral injection from 300 to 7200 for the EGFR+ and from 1300 to 1,100,000 for the HER2+ xenograft." (PMID 29386504, 2018). "We report that while EGFR activation during injury reduces overall tumor burden, receptor activation long after mucosal healing and tumor initiation increases tumor burden." (PMID 29904166, 2018). "The EGFR is therapeutically targeted by agents such as Cetuximab and Erlotinib but the modest effects observed on tumour control have been rather disappointing considering the importance of EGFR-initiated signaling pathways." (PMID 29568372, 2018). "Through this approach, we find that high ST6Gal-I activity enhances EGFR activation, consistent with the vast literature suggesting that ST6Gal-I acts as a tumor-driver gene." (PMID 29402301, 2018). "Activation of EGFR on tumor cells, including NSCLC, also promotes proliferation, invasion, metastasis, anti-apoptotic signaling and angiogenesis in malignant tumors." (PMID 30577587, 2018). "In contrast, deletion of EGFR in the osteoblastic lineage (EgfrΔOb) led to significantly reduced tumor number, size, and lower serum ALP levels, demonstrating that EGFR expression in osteoblasts is essential for OS formation." (PMID 30361264, 2018). "Patients’ age, tumor size, tumor grade, lymph node status, proliferation rate, immunopositivity for EGFR, CK5/6, Ki-67, and disease free survival (DFS) were evaluated statistically." (PMID 29883487, 2018). "The Rab11 effector protein, a Rab-coupling protein, was also reported to be mediated through a mechanism independent of p63 and to result in the enhancement of α5β1-integrin and EGFR in tumor cells." (PMID 29662640, 2018). "The results indicate that downregulation of SCIN inhibited tumour growth and the effect was mediated by EGFR in vivo." (PMID 29744289, 2018). "With this perspective, combinatorial treatment strategies emerged to simultaneously target both the primary tumor’s molecular signature (e.g. EGFR) as well as the signaling mechanism likely to develop (e.g. HER3) upon resistance to first line therapy." (PMID 29899472, 2018).